RNU6-1043P (RNA, U6 small nuclear 1043, pseudogene)
Gene: Small nuclear RNA gene on chromosome 16 (30,701,337 to 30,701,435, reverse strand). Ensembl gene ENSG00000222287.
Homologues: Orthologues: chimpanzee U6 (99% identical), dog U6 (78% identical). Paralogues in human: RNU6-536P (83% identical), RNU6-1024P (82% identical), RNU6-132P (82% identical), RNU6-558P (82% identical), RNU6-589P (82% identical), RNU6-820P (82% identical), RNU6-1083P (81% identical), RNU6-1131P (81% identical), RNU6-12P (81% identical), RNU6-13P (81% identical), RNU6-15P (81% identical), RNU6-19P (81% identical), and 1283 more.